NF1 (neurofibromin 1)
Diseases named in the same sentence as NF1 in open-access papers (continued):
Sharing a sentence is not in itself a finding about the gene and the disease.
neurofibromatosis type 1 (continued). "Neurofibromatosis type 1 (NF1), historically known as von Recklinghausen’s disease, is an autosomal dominant genetic condition caused by mutations in the NF1 gene, with a prevalence of 1 in 3500 individuals in the general population." (PMID 37959212, 2023). "Malignant peripheral nerve sheath tumors (MPNSTs) are rare soft tissue sarcomas, with 50% of cases associated with type 1 neurofibromatosis (NF-1)." (PMID 37842475, 2023). "Patient 1 was a pre-school child with previously unrecognised neurofibromatosis type 1 (subsequently a novel p.Val744AlafsTer3 NF1 variant was revealed)." (PMID 37189994, 2023). "Neurofibromatosis type 1 and pseudoachondroplasia are both rare autosomal dominant disorders, caused by pathogenic mutations in NF1 and COMP genes, respectively." (PMID 36890482, 2023). "Latter more NF1 gene germline mutations that caused neurofibromatosis type 1 diseases have been identified." (PMID 37095468, 2023). "Neurofibromatosis type 1 (NF1) is an autosomal dominant condition caused by germline mutations in the neurofibromin 1 (NF1) gene." (PMID 37990867, 2023). "Both patients with NF1 somatic variants carried a diagnosis of neurofibromatosis type 1 and had known germline variants in the NF1 gene (c.499_502del and c.6904C>T) based on clinical testing." (PMID 37126322, 2023). "Genetic mutations in human NF1 is associated with the disease Neurofibromatosis type 1, which is associated with an increased risk of hypertension." (PMID 37660920, 2023). "One such condition is neurofibromatosis type 1, an autosomal dominant disorder arising from loss of function of the NF1 gene on chromosome 17." (PMID 37185294, 2023). "NF1, also known as von Recklinghausen disease, is an autosomal dominant pathology due to a mutation of the NF1 gene on chromosome 17q11." (PMID 37908901, 2023). "Loss-of-function variants in the NF1 tumor suppressor gene (MIM *613113) cause neurofibromatosis type 1 (NF1, MIM #162200), which has one of the highest spontaneous mutation rates across all monogenic human disorders, described as up to 1 × 10–4." (PMID 37186028, 2023). "Patients with neurofibromatosis type-1 (NF-1) and associated plexiform neurofibromas (PNs) often have a high burden of illness owing to debilitating symptoms of these tumors and limited management options." (PMID 34143343, 2022). "Neurofibromatosis type 1 (NF1) is a genetic disorder caused by mutations in the NF1 tumor suppressor gene (chromosome 17), affecting approximately 1:3500 individuals." (PMID 36497438, 2022). "Neurofibromatosis type 1 (NF1) is an autosomal dominant inherited disorder caused by a germline mutation in the NF1 tumor-suppressor gene." (PMID 36233563, 2022). "Neurofibromatosis type 1 (NF1) is a relatively common autosomal dominant genetic disorder, affecting about 1 in 3000 newborns, and is caused by mutations of the NF1 gene, located on chromosome 17q11.2." (PMID 36015104, 2022). "Another study found that a special imaging feature of some NF1 patients on MRI, the neurofibromatosis type 1 bright objects (NBOs), was correlated with the mutation type of the NF1 gene." (PMID 35677169, 2022). "The most predominant variants of this disease are neurofibromatosis type 1 (NF1), accounting for as many as 96% of cases, and type 2 (NF2), which amounts to 3% of patients respectively." (PMID 35053664, 2022). "Neurofibromatosis type 1 (NF1) is an autosomal-dominant neurogenetic disorder caused by mutations in the gene neurofibromin 1 (NF1)." (PMID 36037004, 2022). "Neurofibromatosis type 1 (NF1) is caused by mutations in the NF1 gene on the long arm of chromosome 17, which affects the skin, nervous system, eyes, and skeleton system." (PMID 36221365, 2022). "Neurofibromatosis type 1 (NF1) is one of the most frequent autosomal dominant disorders and is caused by mutations in the NF1 gene." (PMID 36497448, 2022).
neurofibromatosis type 1 (continued). "Neurofibromin 1 (NF1) is derived from neurofibromatosis type I, which is an autosomal dominant genetic disease with the mutation of the NF1 gene." (PMID 35559021, 2022). "Neurofibromin, whose mutation leads to Neurofibromatosis type 1, is encoded by the NF1 gene and is a Ras-GTPase-activating protein." (PMID 36451655, 2022). "Neurofibromatosis type 1 is an autosomal dominant inherited condition that results from a loss‐of‐function mutation in the NF‐1 gene that encodes Neurofibromin." (PMID 35212097, 2022). "Recently, neurofibromin 1 (NF1) somatic gene mutations or deletions (thought to be the cause of neurofibromatosis Type 1) have been identified in 15–18% of primary GBMs." (PMID 35054779, 2022). "Neurofibromatosis type 1 (NF1) is an autosomal dominant genetic disorder caused by a heterozygous loss-of-function mutation in the NF1 gene." (PMID 33978520, 2022). "Neurofibromatosis type 1 (NF1) occurs as a result of loss-of-function mutations within the NF1 gene." (PMID 35723774, 2022). "Neurofibromatosis type 1 (NF1) is an autosomal dominant genetic disorder caused by pathogenic alterations in the NF1 gene." (PMID 35869419, 2022). "NF1 germline deletions are syndromic for a cancer predisposition referred to as neurofibromatosis type 1." (PMID 35905710, 2022). "Neurofibromatosis type 1 (NF1) is among the most common neurogenic disorders, characterized by loss of function mutations in the neurofibromin gene (NF1)." (PMID 35887576, 2022). "NF1 is a tumor suppressor gene through the down-regulation of the RAS pathway, and mutations lead to neurofibromatosis type 1 (NF1), characterized by the development of multiple benign and malignant tumors." (PMID 36358665, 2022). "Heterozygous NF1 mutations lead to neurofibromatosis type 1 and in a variety of tumors, including juvenile myelomonocytic leukemia." (PMID 35764638, 2022). "Neurofibromatosis type 1 (NF1) or von Recklinghausen disease is an autosomal-dominant genetic disease, caused by a mutation of NF1, localized on chromosome 17." (PMID 35053664, 2022). "We recommend that this unusual variant of NF1 presenting as solitary diffuse neurofibroma around the ankle joint be included among the various clinical manifestations of neurofibromatosis type 1." (PMID 36237736, 2022). "Classified into eight types, the most common type of neurofibromatosis that accounts for 90% of all cases is neurofibromatosis type 1 (NF1), which is underlain by germline mutations in the NF1 gene (locus 17q11.2)." (PMID 35236379, 2022). "Neurofibromatosis type 1 (NF1) is an autosomal dominant neurocutaneous syndrome due to heterozygous pathogenic variants in NF1 gene (17q11.2), that is a de novo variant in half of affected individuals." (PMID 36411470, 2022). "Neurofibromatosis type 1 (NF1, von Recklinghausen’s disease) results from a mutation of the neurofibromin gene (incidence 1:2500–1:3000)." (PMID 36010360, 2022). "Neurofibromatosis type I, a genetic condition due to pathogenic variants in the NF1 gene, is burdened by a high rate of complications, including neoplasms, which increase morbidity and mortality for the disease." (PMID 34427956, 2022). "For example, in neurofibromatosis type 1, an affected individual has a germline mutation in one NF1 allele, and somatic mutations in the second NF1 allele lead to neurofibromas." (PMID 34828306, 2021). "Neurofibromatosis type 1 is a common neurocutaneous syndrome, caused by an alteration of the NF-1 gene, which is a tumor suppressor." (PMID 34539959, 2021). "Neurofibromatosis type 1 (NF1), also known as von Recklinghausen’s disease, is caused by heterozygous inactivating pathogenic variations in the NF1 gene." (PMID 34325699, 2021).
neurofibromatosis type 1 (continued). "Neurofibromatosis type NF1 has been found to be associated with gene mutations, and NF1 gene mRNA levels of specific subtypes are closely related to the severity of neurofibromatosis type 1." (PMID 33673851, 2021). "Neurofibromatosis type 1 (NF1) is an autosomal dominant disorder caused by pathogenic variants in the NF1 tumor suppressor gene." (PMID 33671872, 2021). "Neurofibromatosis type 1 (NF1), also known as von Recklinghausen disease, is an autosomal dominant disease caused by inactivating mutations of the NF1 gene coding a 2818 amino acid protein, neurofibromin (Nfn)." (PMID 34066061, 2021). "Neurofibromatosis type 1, characterized by neurofibromas and café-au-lait macules, is one of the most common genetic disorders caused by pathogenic NF1 variants." (PMID 34573290, 2021). "Neurofibromatosis type 1 (NF1) is caused by heterozygous loss of function mutations in the NF1 gene." (PMID 33673681, 2021). "Neurofibromatosis type 1 is an autosomal dominant genetic disorder caused by mutation in the neurofibromin 1 (NF1) gene." (PMID 34011935, 2021). "Neurofibromatosis type 1 (NF1; MIM#162200), also known as von Recklinghausen disease, is an autosomal dominant disorder caused by loss-of-function mutations in the neurofibromin 1 (NF1) gene." (PMID 34168676, 2021). "In this study, the clinical features of a Chinese patient with neurofibromatosis type 1 were described, and gene sequencing discovered a novel mutation in NF1 gene." (PMID 33764694, 2021). "The patient phenotype is similar to, but milder than, Neurofibromatosis type 1—another RASopathy caused by loss-of-function mutations in the NF1 gene." (PMID 34311771, 2021). "Germline pathogenic variants in NF1 are associated with the autosomal dominant disorder, neurofibromatosis type 1 (NF1), which occurs as commonly as 1 in 2700." (PMID 34771713, 2021). "NF1 was originally discovered in neurofibromatosis type 1, a common developmental disorder caused by germline mutations of NF1 gene." (PMID 35582307, 2021). "Neurofibromatosis type 1 (NF1) gene mutations or alterations occur within neurofibromatosis type 1 as well as in many different malignant tumours on the somatic level." (PMID 35008787, 2021). "Neurofibromatosis type 1 (NF1) is a common autosomal dominant disorder with an incidence of 1:2,7001 caused by a germline pathogenic variant in the NF1 tumor suppressor gene." (PMID 33507822, 2021). "Neurofibromatosis type-1 (NF1) is an autosomal dominantly inherited tumor predisposition syndrome and is caused by a variety of mutations of the NF1 gene." (PMID 33951044, 2021). "Neurofibromatosis type 1 (NF1) is caused by mutations in the NF1 gene, whereas Legius syndrome, also known as NF1-like syndrome, is caused by mutations in the SPRED1 gene." (PMID 34229750, 2021). "Germline NF1 mutations cause the autosomal dominant neuro-cutaneous-skeletal syndrome neurofibromatosis type 1 (NF1), which has an incidence of 1/2000." (PMID 33486672, 2021). "Type 1 neurofibromatosis (NF-1) is due to a mutation of the NF-1 gene and is identified by the presence at different extents of pigmentary skin lesions, neurofibromas, skeletal abnormalities, and brain and peripheral nerve tumors." (PMID 34885063, 2021). "In contrast, patient 10 with a pathogenic NF1 variant only showed slight symptoms of neurofibromatosis type 1 but symptoms consistent with SRS." (PMID 33482836, 2021). "Neurofibromatosis type 1 (NF1) is a complex autosomal dominant disorder caused by germline pathogen variations in the NF1 tumor suppressor gene." (PMID 34809690, 2021). "Heterozygous inactivating mutations in NF1 cause neurofibromatosis type 1, an autosomal dominant neurocutaneous disorder that shows variable clinical expressivity." (PMID 33673681, 2021). "Neurofibromatosis type 1 (NF1) is a rare hereditary tumor predisposition syndrome caused by an autosomal-dominant mutation in the NF1 tumor suppressor gene." (PMID 33446201, 2021).
neurofibromatosis type 1 (continued). "Nonetheless, it should be remembered that atypical neurofibromas in humans are mainly reported in type 1 neurofibromatosis patients in the context of a syndrome that is genetically determined by several mutations of the neurofibromin 1 (NF-1) gene." (PMID 34573587, 2021). "Neurofibromatosis type 1 (NF1) is a genetic disorder caused by pathogenic variants in the NF1 tumor suppressor gene." (PMID 34199217, 2021). "Neurofibromatosis type 1 is an autosomal dominant inherited disease and caused by NF1 gene mutation." (PMID 33764694, 2021). "Neurofibromatosis type 1 (NF1) is caused by heterozygous mutations in NF1 occurring de novo in about 50% of cases, usually due to paternal gonadal mutations." (PMID 32873259, 2020). "Human Neurofibromatosis type 1 is caused by a loss of function of neurofibromin 1, which supposedly functions as a tumor suppressor gene, and leads to multiple cutaneous neurofibroma." (PMID 32552868, 2020). "Many have neurofibromatosis type I (NF1) and NRAS mutations, and sporadic BRAF V600K mutations are also seen." (PMID 32028967, 2020). "Neurofibromatosis type I (NF1) is an inherited autosomal dominant disorder caused by mutation in the tumour suppressor NF1 gene." (PMID 32862562, 2020). "Approximately 50% of neurofibromatosis type I cases have a recognised family history of NF1 mutations." (PMID 32025336, 2020). "Patients with neurofibromatosis type I (NF1) caused by loss-of-function mutations in the NF1 oncogene have hyperactive Ras, and most NF1 children have cognitive deficits." (PMID 33536910, 2020). "Neurofibromatosis type 1 is an autosomal dominant disorder caused by inherited or de novo germline mutations in the NF1 tumor suppressor gene." (PMID 33121128, 2020). "Neurofibromatosis Type 1 (NF1) is caused by germline mutations in the NF1 gene and is the most common single-gene disorder, affecting 1 in 3000 live births." (PMID 32245042, 2020). "Neurofibromatosis type I (NF1) is characterized by prominent skeletal manifestations caused by NF1 loss." (PMID 33177525, 2020). "A recent study demonstrates that SPRED1 interacts with neurofibromin, a protein encoded by NF1, mutation of which leads to neurofibromatosis type 1 (NF1) syndrome." (PMID 32175275, 2020). "Neurofibromatosis type 1 (NF1) is a hereditary cancer syndrome caused by mutations in the NF1 gene, which encodes neurofibromin, a negative regulator of Ras protein." (PMID 32642733, 2020). "Neurofibromin is a large and multifunctional protein encoded by the tumor suppressor gene NF1, mutations of which cause the tumor predisposition syndrome neurofibromatosis type 1 (NF1)." (PMID 33121128, 2020). "Neurofibromatosis type 1 (NF1) is an autosomal dominant genetic disorder caused by mutation in NF1, the tumor suppressor gene encoding neurofibromin." (PMID 33842491, 2020). "Mutations in the NF1 gene can also alter cellular growth and neural development, resulting in neurofibromatosis type 1, an autosomal dominant disorder that affects approximately one in 3,500 newborns worldwide." (PMID 32697994, 2020). "Neurofibromin 1 (NF1) mutations cause an autosomal dominant genetic susceptibility syndrome known as neurofibromatosis type 1." (PMID 33061844, 2020). "Genetic syndromes such as multiple endocrine neoplasia type 1 (MEN1), Von Hippel-Lindau (VHL) and neurofibromatosis type 1 (NF1) have been associated with NENs, but they only account for about 10% of observed cases." (PMID 32245472, 2020). "In this study, we describe for the first time a Neurofibromatosis type 1 patient with pancreas divisum, multiple periampullary tumors and germline pathogenic variants in NF1 and CFTR genes." (PMID 32425982, 2020). "Germline loss of the NF1 tumor suppressor gene underlies the molecular basis of neurofibromatosis type I (NF1), which is characterized by peripheral and central nervous system tumors including GBM." (PMID 33235998, 2020).
neurofibromatosis type 1 (continued). "This is the first report of a Neurofibromatosis type 1 patient with pancreas divisum and multiple periampullary tumors harboring pathogenic germline variants in NF1 and CFTR genes." (PMID 32425982, 2020). "Previous analysis of the NF1 gene in 361 patients with neurofibromatosis type 1 identified four 5’UTR variants as putatively disease-causing." (PMID 32461616, 2020). "Neurofibromatosis type 1 (NF1) and type 2 (NF2) are hereditary, tumor predisposition syndromes that affect multiple systems." (PMID 32642740, 2020). "Neurofibromatosis type 1 (NF1) is an autosomal dominant disease caused by loss-of-function mutations in NF1 gene, which encodes a GTPase activating protein for RAS." (PMID 31234911, 2019). "Germline dominant loss‐of‐function mutations of the NF1 gene cause the common inherited tumor predisposition syndrome neurofibromatosis type 1 (NF1; Online Mendelian Inheritance in Man database 162200)." (PMID 31199580, 2019). "It is well known that Nf1 mutations lead to a common autosomal dominant disorder, neurofibromatosis type 1." (PMID 30906419, 2019). "Neurofibromatosis Type 1 (NF1) is caused by pathogenic variants in the NF1 gene encoding neurofibromin." (PMID 31466283, 2019). "Neurofibromatosis type 1, NF1 is amongst the 16 known causing genes for pheochromocytomas/paragangliomas." (PMID 31551924, 2019). "In this study, we report the bioinformatical and functional evaluation of two novel NF1 variants: c.122A > T and c.7395-17T > G. Both variants were found in neurofibromatosis type I patients." (PMID 31507634, 2019). "Mutations in the NF1 gene cause Neurofibromatosis type 1 a genetic disorder characterized by multiple benign and malignant tumors with prominent neuropsychiatric symptoms including learning and attention deficits, as well as motor impairments." (PMID 31600280, 2019). "Neurofibromatosis type 1 (NF1) is an autosomal dominant condition caused by inactivating mutations of the NF1 gene." (PMID 30843352, 2019). "By characterizing those two novel NF1 splicing variants, we have confirmed the neurofibromatosis type I phenotype in the two probands." (PMID 31507634, 2019). "Neurofibromatosis Type 1 (NF1) occurs in ~1:3500 births due to pathogenic variants in the NF1 gene that encodes the protein neurofibromin." (PMID 31466283, 2019). "Type 1 neurofibromatosis (NF1) is caused by heterozygous mutations in the NF1 gene, and it is characterized by pigmentary lesions (café au lait spots, Lisch nodules, freckling) and cutaneous neurofibromas." (PMID 30828344, 2019). "Defining the pathogenicity of NF1 variants enables appropriate genetic counseling and clinical management of neurofibromatosis type I patients and their relatives." (PMID 31507634, 2019). "Neurofibromatosis type 1 (NF1) (OMIM# 162200) is a disease caused by loss of function mutations in the NF1 gene." (PMID 31507634, 2019). "Most significant enrichment was observed for NF1 (P = 0.000477, OR = 22.8), the gene causal for neurofibromatosis type 1 (NF1), followed by TRPM5, AP5B1, DNMT3L and ARFGEF1." (PMID 31175295, 2019). "We also found two patients with a diagnosis of neurofibromatosis type 1 and mutation of the NF1 gene." (PMID 31083609, 2019). "Neurofibromatosis type 1 is caused by a mutation in the neurofibromin 1 (NF1) tumour-suppressor gene, which comprises 2350 kb and 60 exons on chromosome 17q11." (PMID 31533651, 2019). "One patient with a clinical diagnosis of neurofibromatosis type 1 harbored a germline heterozygous frameshift mutation in the NF1 gene with somatic loss of the remaining wildtype allele in the tumor." (PMID 29880043, 2018). "Neurofibromatosis type 1 (NF1) or Recklinghausen disease is a tumour syndrome caused by alterations in the NF-1 gene." (PMID 30187267, 2018). "Neurofibromas have been classically associated with neurofibromatosis type I (NF-1, Von Recklinghausen’s disease)." (PMID 29426349, 2018).